RN7SKP52 (RN7SK pseudogene 52)
Gene: Miscellaneous RNA gene on chromosome 3 (177,503,303 to 177,503,552, reverse strand). Ensembl gene ENSG00000252028.
Homologues: Orthologues: chimpanzee 7SK (99% identical), guinea pig 7SK (52% identical), mouse Gm54357 (50% identical). Paralogues in human: RN7SKP21 (80% identical), 7SK (66% identical), RN7SKP25 (66% identical), RN7SKP95 (66% identical), RN7SKP128 (65% identical), RN7SKP146 (65% identical), RN7SKP178 (65% identical), RN7SKP187 (65% identical), RN7SKP246 (65% identical), RN7SKP62 (65% identical), RN7SKP80 (64% identical), RN7SKP239 (64% identical), and 283 more.